FGF2 (fibroblast growth factor 2)
Diseases named in the same sentence as FGF2 in open-access papers (continued):
Sharing a sentence is not in itself a finding about the gene and the disease.
glioma (continued). "Moreover, the up-regulation of CD133 may be influenced by EGF and FGF2 in stem cell medium, so what's the influence of hypoxia microenvironment on differentiated glioma cells is not clear." (PMID 28427209, 2017). "Thus, withdrawal of FGF2 did not result in a general decline of gene expression in glioma cells." (PMID 23630597, 2013). "However, the upregulation of FGF2 and NES indicates the presence of an activated microglia phenotype, as these processes such as angiogenesis and cancer stem cell formation are primarily driven by glioma-associated microglia rather than their quiescent phenotype." (PMID 38317968, 2024). "We tested supplementing with epidermal growth factor (EGF) and fibroblast growth factor-2 (FGF-2b), two growth factors used for glioma stem cell maintenance, as well as N2 and B27 without vitamin A, two supplements optimized for neural cell culture." (PMID 35906273, 2022). "In addition, we sorted CD133-CD15- glioma cells three times and cultured cells under hypoxic conditions without EGF and FGF2." (PMID 34976166, 2022). "The data indicated that even without the stimulation of FGF-2, the pro-proliferative effect of GPC1 could be present in U118 glioma cells, which contain high levels of endogenous GPC1 (data not shown)." (PMID 33712571, 2021). "In SEG-1 cells and C6 glioma cells NUDT6 over-expression reduced cellular FGF2 immunoreactivity and inhibited cell cycle progression and proliferation, whereas in rat GH3 pituitary adenoma cells NUDT6 inhibited cell cycle progression and proliferation, but did not suppress FGF2 levels." (PMID 24704982, 2012).
prostate carcinoma (94 papers, 2000 to 2025). A carcinoma that arises from epithelial cells of the prostate gland. "Results of a recent study indicate that high FGF2 levels in osteoblasts (secondary to Tgfβ receptor 2 (Tgfβr2) loss) promote prostate cancer bone metastases in mice." (PMID 32369771, 2020). "Together these studies suggest that loss of Tgfβr2 expression in osteoblasts enables FGF2-mediated crosstalk with prostate cancer cells and promotes bone metastasis." (PMID 32369771, 2020). "Through the application of bioinformatics technology, we identified the potential key genes associated with the occurrence and development of prostate cancer as FGF2, FLNA, VCL, FLNC, CAV1, ACTC1, and MYLK." (PMID 32547947, 2020). "FGF2 was previously reported to be produced by the cells of primary prostate carcinomas with metastasis, and that FGF2 causes the switching of FGFR isoforms from IIIb to IIIc." (PMID 31682640, 2019). "This tumor suppressive activity is associated with 18 kDa LOX-pp, which inhibited FGF-2 signaling in prostate cancer (PCa), oncogenic bcl-2 activity in breast cancer, and nuclear factor-κB (NF-κB) activation in lung and prostate carcinoma." (PMID 29732010, 2018). "Additional studies on tissue sections have revealed that high FGF2 intratumoral levels are associated with advanced tumor stages of bladder, glioma, head and neck, liver, and prostate cancers." (PMID 27007053, 2016). "Our findings show increased risk for all, high-grade, and high-metastasis risk prostate cancer among CC carriers, which are coherent with a functional upregulation of FGF2." (PMID 22792137, 2012). "FGF2 has been described in prostate cancer and implicated in cancer invasion and metastasis, probably through upregulation of MMP9, which was also upregulated in our study." (PMID 18211683, 2008). "PTX3 inhibits the activity of FGF2 or FGF8b, exerting anti-angiogenic and anti-neoplastic activity in prostate cancer." (PMID 41479916, 2025). "Both FGF1 and FGF2 promote glucose uptake by human prostate cancer cells and mouse adipocytes through the MEK/ERK pathway." (PMID 39433211, 2025). "In prostate cancer, FGF2 is substantially upregulated and has a notable influence on the malignant progression of this condition." (PMID 39091947, 2024). "The initiation of fibroblast growth factor 1 (FGF1) expression coincident with the decrease of FGF2 expression is a well-documented event in prostate cancer (PCa) progression." (PMID 38764020, 2024). "Here, EVs isolated from prostate cancer cells were shown to upregulate FGF2 and αSMA in fibroblasts, and EV disruption was found to prevent reactive stroma development in the prostate." (PMID 36671452, 2022). "Of note, the FGF2 acts as a molecular target for Muprafostat oligosaccharide agent, which is currently in phase 2 trial in prostate cancer." (PMID 36468011, 2022). "In comparison, there were no obvious associations between the expression levels of ABHD2, FGF2, DCAF7, GSK3B, NACC2, DICER1, and FGFR1OP genes and survival rate in prostate cancer patients." (PMID 36468011, 2022). "A recent in vitro study showed that Chlamydia trachomatis can proliferate in prostate cancer cells, resulting in enhanced transcription of IL-6 and FGF-2 genes, while FGF-2 can promote vascularization and metastasis of primary prostate cancer." (PMID 34956913, 2021). "Overexpression of miR-16 inhibits FGF2 expression, and miR-16 blocks proliferation and migration of prostate cancer cells by reducing FGF2 expression." (PMID 32411326, 2020). "We showed that endothelial cells-derived FGF2 can induce ERG expression in prostate cancer cells in an AR-independent manner." (PMID 33425737, 2020). "Intriguingly, the expression of FGF2 in endothelial cells was elevated when co-cultured with prostate cancer cells compared with endothelial cells cultured alone." (PMID 33425737, 2020). "Almost all members of FGFs are up-regulated in human prostate cancer, including FGF2, FGF7, FGF10 and FGF1741." (PMID 32139705, 2020).
prostate carcinoma (continued). "Notwithstanding these inadequacies, we still demonstrate that endothelial cells-derived FGF2 plays an important part in promoting docetaxel resistance of prostate cancer cells through in vitro and in vivo experiments." (PMID 33425737, 2020). "Through a combination of cytokines array, quantitative PCR, and ELISA assay, we confirmed that FGF2 was the key factor that facilitated the development of chemoresistance of prostate cancer cells co-cultured with endothelial cells." (PMID 33425737, 2020). "Endothelial cells secrete FGF2 in the tumor microenvironment to enhance the expression of ERG in prostate cancer cells." (PMID 33425737, 2020). "Next, we examined the effect of IL-6, IL-8, CCL5, and FGF2 in the regulation of ERG expression by adding them to the culture media of prostate cancer cells, respectively." (PMID 33425737, 2020). "Taken together, these findings indicated the significance of FGF/FGFR signaling through paracrine FGF2 in a cancer microenvironment for the development and progression of prostate cancer." (PMID 33425737, 2020). "Here, we identified a new signaling pathway that connects FGF2 and docetaxel resistance of prostate cancer." (PMID 33425737, 2020). "For example, the TGF-β-mediated angiogenic effect on xenografts of prostate cancer is regulated by TGFBRII/SMAD3-dependent upregulation of fibroblast growth factor-2 (FGF2) expression and release in prostate stroma." (PMID 28067804, 2017). "Two of these, oleandrin and oleandrigenin, inhibited the catalytic activity of the Na/K-ATPase and inhibited the expression of fibroblast growth factor 2 (FGF-2) in prostate cancer cells." (PMID 29117117, 2017). "Increased serum levels of FGF2 were found in multiple malignancies, including breast, pancreatic, non-small cell lung and prostate cancers." (PMID 28075407, 2017). "For example, FGF-2 and FGF-8 have been implicated in promoting bone metastasis in renal cell carcinoma and prostate cancer, respectively." (PMID 28968431, 2017). "Given that classical FGFs and FGF19 are also increased in prostate cancer, we analyzed expression microarrays hybridized with RNAs from of LNCaP cells stimulated with FGF2, FGF19 or FGF23." (PMID 26019137, 2015). "And data from ONCOMINE prostate cancer database showed that PCa patients with high FGF2 expression showed shorter RFS time (P = 0.046)." (PMID 26650737, 2015). "And data from ONCOMINE prostate cancer database showed PCa patients with high FGF2 expression showed shorter RFS time (P = 0.046)." (PMID 26650737, 2015). "In an animal model of prostate cancer, MSCs were shown to promote fibroblast growth factor 2 (FGF2) secretion by PC3 cells." (PMID 24502410, 2014). "The SNPs in LEPR Gln223Arg, SPP1-66 T>G, IGF1R+3174 G>A, IGFBP3-202 A>C, FGF2+223 C>T and IL6-597 G>A, plus age and PSA remained independently associated with risk for overall, and for high-grade prostate cancer." (PMID 22792137, 2012). "In the prostate cancer group with high risk for metastasis, only the LEPR Gln223Arg, SPP1-66 T>G and FGF2+223 C>T genetic variants, age and PSA persisted." (PMID 22792137, 2012). "Similarly, inhibition of both FGF1 and FGF2 decreases the LDHA/LDHB ratio in prostate cancer cells through the transcription factor STAT1." (PMID 39433211, 2025). "PTX3 may act as an antitumor agent in prostate cancer by targeting FGF2 and FGF8b to exert antiangiogenic and antineoplastic effects, as previously discussed." (PMID 41479916, 2025). "FGF2 knockdown in mice notably delayed the onset and progression of prostate cancer." (PMID 39091947, 2024). "The other genes showing molecular alterations in prostate cancer samples from highest to lowest are as follows; FGF2 (94/4990; 1.9%), NFIB (86/4990; 1.7%), CEP43 (62/4990; 1.2%), GSK3B (99/8961; 1.1%), DICER1 (101/8961; 1.1%), NR3C1 (53/4990; 1.1%) and ABHD2 (28/4,990; 0.6%)." (PMID 36468011, 2022). "Androgen receptor (AR) is known to positively regulate the expression Fgf2 in prostate cancer." (PMID 34957471, 2021).
prostate carcinoma (continued). "Endothelial cells co-cultured with prostate cancer cells can secrete FGF2 into the culture media." (PMID 33425737, 2020). "Interestingly, the expression of FGF2 increased in HUVEC co-cultured with prostate cancer cells compared with HUVEC cultured alone measured by qPCR and ELISA analysis." (PMID 33425737, 2020). "In the co-culture system, the diffusion of growth factors and signal molecules occurs bi-directionally, and it may be possible that HUVEC precondition prostate cancer cells to produce FGF2." (PMID 33425737, 2020). "FGF2 boosts the expression of the ERG gene in prostate cancer cells subsequently." (PMID 33425737, 2020). "Additionally, the amplification percentages of SALL4 (27%) and FGF2 (10%) were determined when the seven-gene signature was analyzed for prostate cancer type, indicating that co-expression genes of OCT4 partially regulates cancer development." (PMID 30287838, 2018). "Moreover, FGF2 expression was elevated in tumor stroma, including inflammatory cells, myofibroblasts, and endothelial cells in colorectal, pancreatic, and prostate carcinomas, respectively." (PMID 27007053, 2016). "Similarly, FGF2 is strongly expressed in the cytoplasm of malignant melanocytes and prostate cancer tissues, while it is almost entirely restricted to the nuclei of benign cells." (PMID 27007053, 2016). "Our findings show that SNPs in genes from adipokine pathways (leptin, interleukin-6, fibroblast growth factor 2, osteopontin, and insulin growth factor) may influence the development of prostate cancer and aggressive disease." (PMID 22792137, 2012). "Thus in prostate development, the initial androgen induction of Sox9 is through Fgf2 signaling, a growth factor also overexpressed in prostate cancer." (PMID 22761195, 2012). "However, the specific mechanism through which FGF1 and FGF2 regulate aerobic glycolysis in prostate cancer remains unclear." (PMID 38764020, 2024). "Furthermore, the importance of Fgf-2 was reported in human prostate cancer progression." (PMID 34686726, 2021). "Furthermore, to investigate whether there was a switch to an autocrine expression by prostate cancer cells in our co-culture model, we performed additional assays of FGF2 expression in 22Rv1 and C4-2B cells in the monoculture and co-culture system." (PMID 33425737, 2020). "Our future approach to determining whether cancer-derived FGF2 is critical in tumor progression is to use knockout mice with either prostate-specific or whole-mouse deletion of FGF2 to determine whether prostate cancer progression in transgenic mouse models is affected." (PMID 33425737, 2020). "FGF-2 is involved in induction of angiogenesis in several cancers; phaeochromocytoma, renal cell carcinoma, astrocytoma, bladder carcinoma, hepatocellular carcinoma, and prostate cancer and also in the signals between the epithelium and connective tissue, influencing growth and differentiation." (PMID 26465941, 2015). "ADAMTS1 suppresses tumor growth in human fibrosarcoma and prostate cancer cells by regulating VEGF and fibroblast growth factor 2, thereby inhibiting angiogenesis." (PMID 40867252, 2025). "Genetic ablation of Fgfr isoforms in MEFs and human prostate cancer cells results in increased OCR, while Fgf2−/− mice exhibit increased WAT and BAT mtDNA copy number." (PMID 39433211, 2025). "For prostate cancer organoid cultivation, A83-01, FGF10, FGF2, prostaglandin E2(PGE2), Nicotinamide and p38 inhibitor SB202190, N-acetylcysteine, B27 and Rho kinase inhibitor Y-27632 were added into the general organoid culture medium." (PMID 37576596, 2023). "Moreover, our results showing the capability of ARV p17 to block FGF-2-induced angiogenesis through the involvement of DPP4 are in line with the previous studies showing the ability of DPP4 to inhibit the malignant phenotype of prostate cancer cells by blocking FGF-2 signaling." (PMID 33525607, 2021).
prostate carcinoma (continued). "In the gene-array experiments using PC-3 (a wild type human prostate carcinoma cell line) clones, silencing FGL2 remarkable downregulates FGF-2, thus inhibiting the occurrence of prostate cancer in mice." (PMID 33867830, 2021). "FGF1, FGF2, FGF6, FGF8, FGF19 and FGF23 are involved in prostate cancer development and progression." (PMID 33655556, 2021). "However, whether prostate cancer cells can secrete FGF2 autonomously is a controversial topic." (PMID 33425737, 2020). "Mechanistically, basic fibroblast growth factor (FGF2) secreted by endothelial cells leads to the upregulation of ETS related gene (ERG) expression and activation of the Akt/mTOR signaling pathway in prostate cancer cells to promote docetaxel resistance." (PMID 33425737, 2020). "Mechanistically, we showed that endothelial cells-derived FGF2 mediated ERG expression and Akt/mTOR activation in prostate cancer cells." (PMID 33425737, 2020). "Recent data indicate that FGF2 and FGF8 stimulate osteoblasts and modulate bone formation in the presence of cancer cells, which in turn increase prostate cancer growth in bone." (PMID 31217507, 2019). "For example, HOXC6 directly regulates gene expression of Bone morphogenetic protein 7 (BMP7), Fibroblast growth factor receptor 2 (FGF2), and Platelet-derived growth factor receptor (PDGFR) in prostate cancer." (PMID 30993034, 2019). "It is also believed that caveolin-1 activates the PI3-K-Akt signaling pathway in prostate cancer cells and promotes cancer cell metastasis by interacting with transfer molecules such as VEGF, TGF-β1 and FGF2." (PMID 30424755, 2018). "Previous observations had shown that FGF8b and FGF2 play a key role in prostate cancer and that PTX3 overexpression inhibits the FGF8b/FGF2-driven growth of TRAMP-C2 tumors, an androgen-responsive murine model of prostate carcinoma." (PMID 25912421, 2015). "In prostate cancer cells, FGFR1 and FGF2 have recently been reported to be post-transcriptionally repressed by the microRNAs miR15 and miR16." (PMID 23185502, 2012). "In prostate cancer, FGFR1 and FGFR4 as well as the ligands FGF-1, FGF-2, FGF-6, FGF-8, FGF-9, and FGF-17 are all known to be over-expressed." (PMID 22078327, 2011). "Given that Perlecan has been shown to modulate the signaling of multiple growth factors including FGF2, FGF10 and VEGF, we asked if the reduction of prostate cancer cell growth in Perlecan siRNA treated cells was a result of decreased SHH signaling." (PMID 16507112, 2006). "FGFR3 binds to multiple FGFs known to be upregulated in human prostate cancer (FGF1, FGF2 and FGF8), and is potentially important in prostate cancer." (PMID 15655558, 2005). "Overexpression of multiple FGFs (namely aFGF/FGFl, bFGF/FGF2, FGF6 and FGF8) has been identified in prostate cancer." (PMID 15655558, 2005). "Similarly, inhibition of both FGF1 and FGF2 decreases lactate production, as well as the basal and maximal ECAR in prostate cancer cells." (PMID 39433211, 2025). "FGF2 is also upregulated in prostate cancer and a ribozyme-targeting approach to selectively deplete FGF-binding protein (FGF-BP) to reduce FGF2 mobilization and activation from the ECM has been shown to prevent PC-3 xenograft tumor formation in athymic nude mice." (PMID 36671452, 2022). "Taken together, these results revealed that FGF2 derived from HUVEC might represent the primary source of FGF2 in the co-culture system and play a key role in inducing the expression of ERG and promoting chemoresistance to docetaxel in prostate cancer cells." (PMID 33425737, 2020). "Specifically, we demonstrated that FGF2 secreted from endothelial cells can upregulate ERG expression in prostate cancer, which then activates the Akt/mTOR signaling pathway and promote docetaxel resistance of prostate cancer subsequently." (PMID 33425737, 2020). "The indicated docetaxel treatment did not cause the expression of FGF2 in HUVEC and prostate cancer cells in the co-culture system." (PMID 33425737, 2020).